SRARP (steroid receptor associated and regulated protein)
Description:
May regulate the transcriptional function of androgen and estrogen receptors.
Synonyms: C1orf64; ERRF; MGC24047
Tractability: No criterion of Open Targets' tractability assessment is met for any kind of drug.
Gene: Protein-coding gene on chromosome 1 (16,004,236 to 16,008,807, forward strand). Ensembl gene ENSG00000183888.
Subcellular location (Human Protein Atlas): Nucleoplasm
Gene Ontology:
Molecular function: nuclear estrogen receptor binding; protein binding
Biological process: positive regulation of intracellular estrogen receptor signaling pathway
Cellular component: cytoplasm; nucleus
Genetic constraint (gnomAD): Loss-of-function variants: 6 observed, 4.67 expected, observed/expected ratio (o/e) 1.29, 90% interval 0.67 to 1.9. That is too few expected variants to judge how well the gene tolerates losing a copy. Missense variants: 207 observed, 216.87 expected, observed/expected ratio (o/e) 0.95, 90% interval 0.85 to 1.07. Synonymous variants: 89 observed, 90.54 expected, observed/expected ratio (o/e) 0.98, 90% interval 0.83 to 1.17.
Homologues: Orthologues: chimpanzee SRARP (99% identical), macaque SRARP (92% identical), pig SRARP (63% identical), rabbit SRARP (63% identical), dog SRARP (61% identical), guinea pig SRARP (60% identical), mouse Srarp (44% identical), rat Srarp (44% identical).